COL4A1 (collagen type IV alpha 1 chain)
Diseases named in the same sentence as COL4A1 in open-access papers (continued):
Sharing a sentence is not in itself a finding about the gene and the disease.
tumor (continued). "Genes in the high expression groups, namely, COL1A1, COL4A1, COL12A1, and PDGFRB, were all enriched in the MAPK and PI3K–Akt signaling pathways, which are closely associated with tumor cell proliferation, invasion, and cell cycle." (PMID 35111208, 2021). "The expression of vascular basement membrane markers, Col4a1 and Col4a2, increased dramatically upon tumour infiltration." (PMID 34836954, 2021). "We validated four gene fusions by PCR amplification of the predicted breakpoint junction from tumour cDNA: COL4A1‐VEGFD, SRF‐ICA1L, SRF‐CITED1 and MTCH2‐FNBP4." (PMID 33830670, 2021). "The stained tissue sections demonstrated that the expression of VEGFD was robust in the P38 tumour sample, bearing the COL4A1‐VEGFD gene fusion, compared to patient P46, used as negative control." (PMID 33830670, 2021). "Quantitative analysis of our RNA sequencing data showed that the strong expression of COL4A1 in myofibroma enables the expression of VEGFD specifically in tumours harbouring the COL4A1‐VEGFD fusion gene." (PMID 33830670, 2021). "Of the mutated genes found important to cell adhesion, genes such as Col4a1 are important components of the basement membrane and are involved in tumor progression." (PMID 33947907, 2021). "Other differentially expressed genes encode proteins involved in the suppression of angiogenesis, induction of tumor cell apoptosis, and decreased tumorigenicity, including COL4A1 (arresten), COL4A2 (canstatin), and COL4A3 (tumstatin)." (PMID 32842611, 2020). "The deposition of COL4A1 protein can activate the ITGB1 signaling pathway in tumor tissues, and then the elasticity and adhesion ability of cancer cells are reduced." (PMID 32637572, 2020). "We enrolled 206 BC patients to estimate COL4A1 protein detected using immunohistochemistry in 206 paired tumor and adjacent normal breast tissue." (PMID 32565804, 2020). "Of the 206 pairs, the expression level of COL4A1 in the tumor tissue was higher than in the normal tissue from the 161 pairs (161/206, 78%)." (PMID 32565804, 2020). "Low COL4A1 expression in the tumor cells of BC patients was found to significantly reduce the overall survival (OS) and relapse-free survival (RFS) rates of neoadjuvant chemotherapy patients (P=0.047 and P=0.025, respectively)." (PMID 32565804, 2020). "The expression of the COL4A1 protein was significantly higher in normal adjacent tissue than in the tumor tissues of BC (P < 0.0001)." (PMID 32565804, 2020). "Upon proteolytic cleavage of COL4A2 and COL4A1, biologically active peptides called Arresten and Canstatin, respectively, are formed that inhibit angiogenesis, proliferation and tumor formation." (PMID 31778112, 2019). "In the endometrium, the breakdown of the basement membrane as well as increased expression of COL4A1 have been related with inhibition of angiogenesis and reduced tumor growth." (PMID 29118976, 2017). "A couple of previous reports demonstrated that COL4A1 plays an important role in angiogenesis and tumor progression." (PMID 28415608, 2017). "An example of a tumor with a trabecular pattern shows heterogeneous COL4A1 expression in the stroma around the tumor lesion (upper-middle panel)." (PMID 28415608, 2017). "miR-140 also contributes to tumor suppressive effect by targeting COL4A1, ITGA6 and MARCKSL1 in breast cancer." (PMID 29162923, 2017). "The present study investigated the association of COL4A1 and COL13A1 with tumor invasion and progression using in vitro and in vivo experimental models and clinical materials of human UCB." (PMID 28415608, 2017). "The COL4A1 and COL4A2 had the most significant association with tumor grade (AUC = 0.822 and 0.820 in G2 vs G3 and G4; AUC = 0.863 and 0.834 in G3 vs G4), followed by COL4A3 and COL4A4 (AUC = 0.539 and 0.585 in G2 vs G3 and G4; AUC = 0.677 and 0.753 in G3 vs G4)." (PMID 40351420, 2025).
tumor (continued). "Interestingly, the extracellular matrix protein-encoding genes such as FN1, TIMP1, COL3A1, COL4A1, and COL2A1 were discovered in spatial cluster 8, regarded as tumor stroma tissues." (PMID 39257581, 2024). "Interestingly, the COL4A1 gene was hypomethylated in ccRCC tumor samples compared to adjacent normal tissue." (PMID 39639369, 2024). "Our results suggested that COL4A1/2/3/4 may play a role in tumor immunosuppression and may have great potential as immune infiltration markers with important implications for tumor diagnosis and target development." (PMID 38907304, 2024). "The analysis suggested that TECs might promote tumor growth and progression through the interaction of COL4A1/COL4A2 with their partner receptors (ITGAV + ITGB8 and ITGA3 + ITGB1) on epithelial cells." (PMID 39093451, 2024). "COL4A1, is implicated in ECM remodeling and tumor microenvironment alterations." (PMID 39850811, 2024). "However, another study reports that reducing the BM stiffness by targeting Col4a1 enhances tumor invasion in the mouse model." (PMID 37864030, 2023). "Indeed, multiplex immunofluorescence experiments were also performed and validated the increased colocalisation of SDC1 and COL4A1 in the recurrent group, mainly in the tumour region." (PMID 37488671, 2023). "Interestingly, we also anlysized peritoneal metastases from GCPM patients and found that CD93, COL3A1, COL4A1 expression were higher in metastases than in the primary tumor." (PMID 36690975, 2023). "In summary, lnc-RFNG-1, lnc-TRIM28-14, CD93, COL3A1 and COL4A1 could be novel tumor biomarkers and potential therapeutic targets for GCPM." (PMID 36690975, 2023). "We further found that expression of CD93 was correlated with tumor size, differentiation and peritoneal metastasis; that of COL3A1 was correlated with differentiation, depth of invasion, peritoneal metastasis and TNM stage; that of COL4A1 was correlated with tumor size and peritoneal metastasis." (PMID 36690975, 2023). "Moreover, tissue-wide RNA microarray data revealed that COL4A1 was overexpressed in 21 tumor tissues." (PMID 35455650, 2022). "Notably, tumor ECs were featured by upregulation of angiogenesis-related genes including collagens (e.g., COL4A1, COL4A2), PXDN, SPARC and HSPG2, as well as proliferation markers (e.g., MKI67, TOP2A)." (PMID 36138435, 2022). "Moreover, to confirm the role of COL4A1 expression in immune infiltration into the TME during tumor growth, further in vitro and in vivo studies should be conducted in the future." (PMID 35455650, 2022). "Additionally, COL4A1 expression was highly correlated with the signatures of CAFs and endothelial cells in all four tumor types." (PMID 35455650, 2022). "Aberrant expression of collagen type IV alpha chain 1 (COL4A1) can influence tumor cell behavior." (PMID 35455650, 2022). "We amplified and cloned the full COL4A1‐VEGFD open reading frame from patient P38 tumour cDNA." (PMID 33830670, 2021). "Tumor metastasis correlated with worse prognosis, and COL4A1 expression in BC patients who received neoadjuvant chemotherapy could predict favourable OS and RFS as assessed via the Kaplan–Meier method." (PMID 32565804, 2020). "Based on promotion effects of upregulation of COL4A1 in tumor growth through activating FAK-Src signaling in HCC cells, we wonder if FAK or Src inhibitor could effectively suppress the growth of HCC cells with high expression of COL4A1." (PMID 32746865, 2020). "Moreover, we conducted subcutaneous xenograft tumor experiments in nude mice, and results showed that knockdown of COL4A1 significantly reduced the growth of subcutaneous xenograft tumors derived from SMMC7721 cells." (PMID 32746865, 2020). "Upregulated COL4A1 promotes tumor invasion via induction of tumor budding in bladder cancer cells." (PMID 32746865, 2020). "We observed a COL4A1 downregulation in both Etoposide resistant RB cell lines, which seems to be in contrast with the observed upregulation and functional relevance in various tumor types." (PMID 32560557, 2020).
tumor (continued). "This suggested that upregulation of the COL4A1 may had an important influence on cell behavior in the tumor microenvironment." (PMID 32637572, 2020). "Gene expression analysis of paired tumor-non-tumor samples from TCGA-LIHC cohort (n = 438) also showed 1.13-(p < 0.001), 1.01-(p < 0.01), and 1.07-(p < 0.001) fold reduction in COL1A1, COL1A2 and COL4A1 mRNA expression in the HCC tumor compared to the non-tumor ‘normal’ liver samples." (PMID 31181620, 2019). "The increased availability of Mmp2 and Mmp12 as well as their substrates Col1a1, Col4a1, Col6a1 and LamC2 could indicate that the tumour cells generated foremost collagens, which can be cleaved by these Mmps." (PMID 30603057, 2018). "Previous studies pointed to the effect of COL4A1 in tumor progression and metastasis." (PMID 27502506, 2016). "Thus, it is unclear whether targeting Col4a1 affects tumor cell invasion through the effect on BM stiffness or composition." (PMID 37864030, 2023). "In this study, using various bioinformatics databases available from public resources, we analyzed the levels of COL4A1 expression in 33 types of tumor tissues and examined whether elevated COL4A1 levels are associated with poor prognosis depending on the type of tumor." (PMID 35455650, 2022). "Interestingly, HNSCC patients with higher COL4A1 expression showed a better disease-free survival in our study, indicating that COL4A1 could plays an inhibitory role in tumor recurrence." (PMID 35046992, 2021). "Genes encoding collagens (COL4A1, COL4A2), collagen-modifying enzyme (PXDN), and other components of the basement membrane (LAMB1, HSPG2) also ranked in the top 10 most enriched Co1 EC markers, indicating that extensive matrix remodeling occurs in GBM during tumor angiogenesis." (PMID 34228647, 2021). "Last but not least, SRF, a tumor-associated transcription factor, may also involve in hepatocarcinogenesis induced by COL4A1 and COL4A2." (PMID 31905170, 2020). "A comparison of these with the 683 KPTN tumor–upregulated genes revealed 130 consistently upregulated genes, including ECM components (COL4A1, COL4A2, COL12A1, VCAN, etc.)and YAP targets (ANKRD1, AXL, CYR61, F3)." (PMID 41480763, 2026). "The mRNA expression analysis revealed that THBS2, CTNNB1, COL4A1, and E2F3 were significantly upregulated in tumor tissues compared to normal gastric tissues in the TCGA-STAD cohort." (PMID 41291892, 2025). "Therefore, the increased vessel formation in tumors may be associated with the upregulation of COL4A1 and COL4A2 expression, and the aggressiveness of the tumor may result in the downregulation of COL4A3 and COL4A4 expression and minor Col IV degradation to promote invasion of tumors." (PMID 40351420, 2025). "In vivo, METTL16 overexpression induces tumor growth, increases LAMA4 and COL4A1 expression, and enhances cisplatin resistance." (PMID 41322419, 2025). "Promoter methylation analysis using the UALCAN database revealed that THBS2, CTNNB1, COL4A1, and E2F3 exhibited significantly lower promoter methylation levels in STAD tumor tissues compared to normal controls." (PMID 41291892, 2025). "The results demonstrated that COL4A1 and COL4A2 exhibited higher expression levels in tumor samples compared to normal tissues." (PMID 38907304, 2024). "For stromal cells, we identified four mural cell subclusters (CCL19+ pericytes, RGS5+ pericytes, COL4A1+ smooth muscle cells [SMCs], and MYH11+ SMCs) and two EC subclusters (peripheral ECs and tumour core ECs)." (PMID 38943472, 2024). "COL4A1 (collagen alpha-1(IV) chain) captures structures containing the C-terminal NC1 domain, inhibiting angiogenesis and tumor formation." (PMID 38994496, 2024). "To further characterize the presence of COL4A1 and ITGAV in ccRCC, we examined the Clinical Proteomic Tumor Analysis Consortium (CPTAC), The Cancer Genome Atlas (TCGA), and the Genotype-Tissue Expression (GTEx) project." (PMID 39639369, 2024).
tumor (continued). "We demonstrated that stromal colocalization of ITGAV and COL4A1 in the IO-exposed TIME is increased among fibroblasts, tumor cells, and endothelial cells." (PMID 39639369, 2024). "The RGS5+ CAFs in our study (which we appointed a T cell-exclusion role from tumor nests) also expressed MYH11, ACTA2, and COL4A1." (PMID 39516494, 2024). "To validate the mRNA expression pattern, we compared the protein expression levels of COL4A1 and COL4A2 between tumor cells and normal cells." (PMID 38907304, 2024). "Along the tumor-stroma boundary, extracellular matrix genes fibronectin (FN1) and collagen type 4 alpha 1 (COL4A1) are highly expressed in fibroblasts and endothelial cells, respectively." (PMID 37426750, 2023). "Gene expression of COL1A1, COL1A2, COL6A3, FN1, and THY1 in CAFs as well as COL4A1 and COL4A2 in Angiogenic_EC had a highly significantly positive correlation with the proportion of malignant tumor cells." (PMID 38002057, 2023). "We found that NOVA2 expression is significantly correlated to that of Collagen type IV Alpha 1 Chain (COL4A1), a poor prognosis angiogenic marker for GC, raising the possibility that NOVA2 was selectively overexpressed in tumor ECs." (PMID 37175811, 2023). "The collagen type IV alpha 1 chain (COL4A1) is the most significantly overexpressed collagen in HCC and facilitates tumor aggressiveness of HCC cell lines (HepG2, PLC/PRF/5, Hep3B, and SK-Hep1) by activating FAK-Src signaling." (PMID 38201459, 2023). "COL4A1, COL6A3, FAP, and LY6E were up-regulated in the tumor group in the training set, whereas ABCA8, MAMDC2, TMEM100, and TMEM266 were down-regulated." (PMID 36685898, 2022). "We then analyzed the expression profiles of COL1A1, COL4A1, and COL6A2 in TAF and ITGA2, ITGAV, and ITGA1 in tumor cells." (PMID 35322024, 2022). "FN1, ITGA5, THBS2, and LAMA1 were associated with cell adhesion and metastasis, and the expression of TGFB1, COL4A1, COL4A2, and THBS2 inhibited tumor growth." (PMID 34370778, 2021). "The key genes COL1A1, COL4A1, COL5A2 belong to the collagen family, which is a constituent of the ECM component of tumors, and is closely related to tumor proliferation, invasion, drug resistance, and prognosis 7,40-46." (PMID 33976737, 2021). "The results revealed that COL1A1, COL4A1, COL12A1, and PDGFRB were all negatively correlated with tumor purity." (PMID 35111208, 2021). "The expression of COL1A1, COL4A1, COL12A1, and PDGFRB were all negatively correlated with tumor purity." (PMID 35111208, 2021). "The ECM components COL1A1, COL3A1, COL4A1, and fibronectin 1 (FN1), are critical regulators during tumor metastasis, so we examined their expression in the DCN and control cells using qPCR." (PMID 34504839, 2021). "We performed differential analysis and correlation analysis of these four genes (COL3A1, COL4A1, COL5A1, and COL15A1) and tumor immune subtypes with tumor microenvironment scores." (PMID 34691289, 2021). "In our NCKU-OrCA-40TN cohort, we noticed that five collagen subunits are upregulated genes in the tumor tissues compared to that in the normal counterparts, including COL1A1 (3.5×), COL4A1 (2.1×), COL4A2 (3.3×), COL4A5 (5.6×), and COL4A6 (9.2×)." (PMID 32244515, 2020). "Nevertheless, poorly differentiated cell lines mimicked upregulated expression of genes (in tumours) such as CAV1, COL4A1, and novel candidates such as TSPAN5, TENM2, C15orf48, PLAU, AHNAK2, FAM129A, PLAU and platelet-specific phosphofructokinase (PFKP)." (PMID 30176945, 2018). "COL4A1 and COL13A1 production by cancer cells plays a pivotal role in tumor invasion through the induction of tumor budding." (PMID 28415608, 2017). "COL4A1 and COL13A1 predominantly localized to the stromal area around the tumor site and the cytoplasm of tumor cells, respectively." (PMID 28415608, 2017). "Among the genes involved in the hepatic fibrosis pathway, expression of the IGFBPs, COL4A1, COL4A2, MMP9 and TNFRSF11B was restored in 143BNSC and 143BGBM tumours." (PMID 27551510, 2016).
tumor (continued). "In this analysis, we identified subtype‐specific events for Epi‐LumB tumors involving either DNA copy number loss or CpG promoter methylation over DZIP1, TNFSF11, ZIC5, COL4A2, COL4A1 and PCDH8 indicating candidate tumor suppressor genes." (PMID 25468711, 2015). "And COL4A1, as an essential component of ECM, plays an important role in angiogenesis and tumor progression." (PMID 25887589, 2015). "Furthermore, mutation and CNV analyses revealed frequent genomic alterations in these genes, especially COL4A1 and CTNNB1, reinforcing their potential as drivers of tumor evolution." (PMID 41291892, 2025). "Applying similar tumor microenvironment oriented analytical strategies to THBS2, CTNNB1, COL4A1, and E2F3 may offer deeper insight into their roles in shaping immune suppression, stromal remodeling, and treatment response in STAD." (PMID 41291892, 2025). "COL4A1 and THBS2 showed strong positive correlations with immunosuppressive cells, such as macrophages and myeloid-derived suppressor cells (MDSCs), reinforcing their potential role in establishing an immune-tolerant tumor microenvironment." (PMID 41291892, 2025). "Finally, ECM and fibrosis-related molecules (COL1A1, COL4A1, COL6A3, fibronectin, and LAMC1) were elevated, closely mimicking the desmoplastic tumor microenvironment of HCC." (PMID 41149589, 2025). "Further studies revealed that the hub genes MRPL20, COL4A1, and VWF played key roles in tumor energy metabolism, cell adhesion, and angiogenesis, showing the possibility of inhibiting BC cell development and metastasis by regulating these genes and their interactions." (PMID 39529627, 2024). "Spatial transcriptomics of samples of 3 patient cohorts with cRCC tumors indicates that COL4A1 and ITGAV are more autocorrelated in immunotherapy-exposed stroma compared to immunotherapy-naïve tumors, with high expression among fibroblasts, tumor cells, and endothelium." (PMID 39639369, 2024). "On comparison of paired tumor versus non-tumor tissue from the same livers, the fibrosis gene panel showed five genes significantly up-regulated in tumors (Pdgfb, Mmp14, Alb, Col4a1 and Pecam)." (PMID 39254423, 2024). "However, recent studies have revealed that the expression levels of COL4A1 in the TME have a positive relationship with drug resistance and tumor recurrence or progression in certain types of cancer." (PMID 35455650, 2022). "COL4A1 expression was also significantly correlated with the expression levels of T cell exhaustion marker genes such as PDCD1, CTLA4, LAG3, and HAVCR2 in all the four tumor types with only two exceptions (CTLA4 in SKCM and LAG3 in STAD)." (PMID 35455650, 2022). "The mRNA expression level of all six type IV collagen genes (COL4A1, COL4A2 COL4A3, COL4A4, COL4A5 and COL4A6) was higher in metastatic tissue compared to primary tumor tissue, although being significant only for COL4A3 (p = 0.013) and COLA4A4 (p = 0.005) genes." (PMID 35693557, 2022). "Both COL4A1 and COL4A2 influence angiogenesis and tumor growth." (PMID 33927218, 2021). "The COL4A1‐VEGFD fusion leads to production of mature VEGFD after proteolytic processing, which may act as an autocrine growth factor for tumour cells." (PMID 33830670, 2021). "Moreover, the mRNA levels of both COL4A1 and COL4A2 were significantly increased in subgroups of HCC patients classified by ethnicity, gender, age, tumor grade, and disease stages compared to normal people." (PMID 31905170, 2020). "COL4A1, an essential component of the ECM that is also involved in the ECM-receptor interaction and focal adhesion pathway, has an essential role in angiogenesis, inflammation, and tumor progression." (PMID 32801999, 2020). "The muscle invasive tumour, however, showed a basal subtype (higher expression of CDH3, CD44, KRT5 and KRT6A) and likewise high aggressiveness (higher expression of KPNA2, BIRC5, CDC25B, COL4A1, and MSN)." (PMID 28916750, 2017).